MIR548AJ1 (microRNA 548aj-1)
Synonyms: hsa-mir-548aj-1
Gene: MicroRNA gene on chromosome 6 (132,115,192 to 132,115,263, reverse strand). Ensembl gene ENSG00000265669.
Homologues: Orthologues: chimpanzee MIR548AJ1 (100% identical). Paralogues in human: MIR548H3 (83% identical), MIR548AH (82% identical), MIR548X2 (82% identical), MIR548AX (81% identical), MIR548O2 (81% identical), MIR548Z (81% identical), MIR548AN (79% identical), MIR548AY (78% identical), MIR548X (78% identical), MIR548AZ (76% identical), MIR548P (76% identical), MIR548S (76% identical), and 13 more.